REN (renin)
Diseases named in the same sentence as REN in open-access papers (continued):
Sharing a sentence is not in itself a finding about the gene and the disease.
tumor (continued). "PPAR-Riskscore was constructed by univariate Cox regression based on the expression of 4 genes (NR1D1, ILK, TNFRSF1A, and REN) in tumor tissues." (PMID 35481240, 2022). "Increased renin–angiotensin system activity is known to increase blood pressure and to induce immunosuppression in the tumor environment." (PMID 34771631, 2021). "In keeping with results of functional studies, and with the detection of renin and the AT-1R in such tumours, we detected Ang II also in some APA and APA-adjacent tissues suggesting that the peptide can play a role in human PA." (PMID 33657582, 2021). "Theoretically, neoangiogenesis is one of the key pathogenic mechanisms in hepatic cancer, and modulation of the renin-angiotensin-aldosterone system seems to be a possible anti-tumor mechanism of the anti-angiogenic and anti-fibrogenic activity of ARBs." (PMID 33671916, 2021). "Data suggest that renin–angiotensin system signaling stimulates the tumor's immune microenvironment to impact overall survival." (PMID 33554099, 2021). "RAS components are expressed by most immune cells and adult hematopoietic cells, thus are potential targets for modulating tumor-infiltrating immune cells and can provide a mechanism of tumor control by the renin–angiotensin system inhibitors (RASi)." (PMID 32448803, 2020). "This secondary hypertension results from an increased plasma concentration of renin, which is produced by areas of the kidney cortex entrapped within the tumor." (PMID 32056027, 2020). "Our results found that adjusting the acidic pH of the conditioned medium of hypoxic CNE2 and 5–8F tumor cells remarkably increased lactate production which promoted Ang II generation by inducing expression of chymase and renin." (PMID 28205588, 2017). "At least 3 of the cases had well-differentiated tumor types and, interestingly, in one of the tumors renin secreting cells were found." (PMID 28079820, 2017). "One other aminopeptidase associated with tumor progression and metastasis is aminopeptidase N (APN/CD13), which is downstream of APA in the renin-angiotensin system." (PMID 28177885, 2017). "The following case report describes an exceedingly rare tumor in an even more rare age demographic: an ectopic renin‐secreting adrenal adenoma in a 7‐year‐old male child presenting with hypertensive emergency." (PMID 26997629, 2016). "Sections of the tumor were subsequently stained for renin using a rabbit polyclonal antibody (Anaspec, Fremont, CA)." (PMID 26997629, 2016). "The tumor section exhibited several renin positive (red) cells containing large renin storage granules." (PMID 26997629, 2016). "After surgical removal, the tumor stained positive for renin, suggesting an ectopic source of renin secretion." (PMID 26997629, 2016). "The diagnosis of a renin-secreting tumor is usually determined by positive immunostaining of renin or by electron microscopic identification of renin granules." (PMID 25289084, 2014). "The elevated renin level at presentation fell following successful treatment of the primary tumor, which strongly indicates that the tumor was the source of the renin." (PMID 25289084, 2014). "In designing the optimal approach for our patient and her renin-secreting tumor, we appreciated the likely benign nature of this lesion." (PMID 25177679, 2014). "In total, ~40 patients with a renin-producing tumor (excluding lesions of the juxtaglomerular apparatus) had been reported by 1988 and the majority were of renal origin." (PMID 25289084, 2014). "The diagnosis was confirmed by electron microscopy revealing the presence of rhomboid dense deposits (renin crystals) in the cytoplasm of the tumor cells." (PMID 25177679, 2014). "During the progression from normal to malignant phenotypes, the angiotensin II type 1 receptor is often up-regulated, which suggests a correlation between the renin-angiotensin system and tumor progression." (PMID 24465768, 2014).
tumor (continued). "Although an immunohistochemical evaluation of renin was not conducted as the sample size was inadequate, the present study demonstrated that the tumor had produced renin." (PMID 25289084, 2014). "Electron microscopy revealed renin deposits in the cytoplasm of the tumor cells, confirming the diagnosis of reninoma." (PMID 25177679, 2014). "Following the confirmation of the renin-producing tumor in the left kidney, surgical resection of the tumor was performed." (PMID 25177679, 2014). "Since Angiotensinogen is the precursor form of the active peptide Angiotensin, the pair AGT-AGTR1 makes up the renin-angiotensin system (RAS), usually associated with cardiovascular homeostasis but recently associated with tumor growth." (PMID 24597571, 2014). "Ultrastructurally, the tumor cells contained rhomboid-shaped granules in the cytoplasm, consistent with renin protogranules." (PMID 23607027, 2013). "Pathologically, the tumor was composed of cuboidal cells forming a solid arrangement, immunohistochemically positive for renin." (PMID 23607027, 2013). "We also found a positive correlation with the renin-angiotensin system, a process reported to be involved in regulation of tumour angiogenesis in ER-negative breast cancers." (PMID 24059244, 2013). "The cytoplasm of tumor cells contains characteristic rhomboid-shaped renin protogranules, abundant rough endoplasmic reticulum and prominent Golgi apparatus." (PMID 21871063, 2011). "Immunoreactive renin was found in the cytoplasm of media cells in small blood vessels of human pulmonary tumors, and in a derived human tumor cell line, CaLu-6, that expresses the human renin gene endogenously." (PMID 20948562, 2010). "Abundance of (pro)renin also varied according to the stage of malignancy, suggesting that its expression varied inversely with tumour grading." (PMID 16755291, 2006). "In a group of 19 patients in whom nuclear oestrogen receptor (REN) was also estimated in the pellets from tumour-tissue homogenates, 5/6 with tumours positive for all 3 receptors showed a clinical response." (PMID 230853, 1979). "Atypical cases, such as the present one, may exhibit normal renin, aldosterone, and potassium levels despite the presence of a functional tumor." (PMID 41357681, 2026). "The renin–angiotensin system, traditionally known as an endocrine system for its role in cardiovascular homeostasis, is increasingly appreciated to play a key role in regulating CSCs within the tumor microenvironment (TME) in a paracrine fashion (paracrine renin–angiotensin system)." (PMID 39941158, 2025). "This suggests that renin in the surgically removed tumor tissue is not the cause of the BP reduction in hypertensive patients." (PMID 40959573, 2025). "For example, angiotensin II, a major signalling molecule of the renin-angiotensin system, can promote tumour growth by inducing angiogenesis and tumour cell proliferation through increased expression of vascular endothelial growth factor (VEGF) or epidermal growth factor receptor (EGFR)." (PMID 38487860, 2024). "The tumor is also called reninoma because it can secrete renin." (PMID 38365645, 2024). "Gastrin, pituitary and target gland axis hormones, blood and urine catecholamines and their metabolites, aldosterone-renin-angiotensin system, fasting blood glucose, insulin, C-peptide, complete blood count, liver and kidney function, urinalysis, and tumor markers were all normal." (PMID 39371924, 2024). "This type of secondary hypertension occurs either through activation of the renin-angiotensin-aldosterone system (RAAS) due to the proliferation of juxtaglomerular cells in the kidney or through renal artery narrowing resulting from tumor growth." (PMID 39650950, 2024). "The study suggested that activations of the tissue renin-angiotensin system (RAS) are associated with the pathogenesis of conjunctival MALToma by stimulating subsequent events involving extracellular matrix turnover and tumor angiogenesis." (PMID 39338181, 2024).
tumor (continued). "Examining these data, first, we asked whether each tumour cell transcribed more renin than normal mesangial-like cells." (PMID 37749094, 2023). "ARB also decreased the cancer-related fibroblasts, chemokine ligand 12, and nitric oxide synthase 2 expressions, indicating that the renin-angiotensin-system is involved in the production of immunosuppressive cells initiated by bone marrow cells and fibroblasts tumor microenvironment." (PMID 37680706, 2023). "There is increasing evidence that activation of the classical renin-angiotensin system pathway through Angiotensin II-angiotensin-1-receptor (AT1R) drives tumor progression through enhanced tumor proliferation, migration, invasion and angiogenesis, as well as inhibition of apoptosis." (PMID 37370793, 2023). "This is supported by the consistent up-regulation of REN only in later stage tumor samples." (PMID 35659616, 2022). "Juxtaglomerular cell tumor is a benign, renin-secreting neoplasm." (PMID 36312876, 2022). "Hypertension in RCC occurs due to an increase in production/secretion of renin, and/or by direct compression of the renal artery/distal branches (extrinsic compression or tumor invasion leading to renal artery stenosis), and/or secondary to arteriovenous fistula formation within the tumor." (PMID 36428491, 2022). "REN was up-regulated in all later stage (stages 3 and 4) tumor samples." (PMID 35659616, 2022). "In addition, AQP6 function was also examined because its significant upregulation in stromal tumor tissue was reported, but our results show a reduced expression in REN and MSTO-211H compared with MeT-5A." (PMID 35741021, 2022). "However, recent investigators have identified mechanisms by which the renin–angiotensin aldosterone system impacts the tumor cell microenvironment." (PMID 33554099, 2021). "Additionally, the renin-angiotensin system has also been shown to regulate various aspects of tumor growth and development including: cell proliferation, angiogenesis, inflammation, and apoptosis." (PMID 34121975, 2021). "Angiotensin-converting-enzyme (ACE) inhibitors through renin–angiotensin system inhibition may reduce tumor progression and potentially affect SI-NEN-related MF." (PMID 32521677, 2020). "Collectively, increased activity of local brain renin–angiotensin system may promote a dysregulated tumor vasculature resistant to bevacizumab‐induced vascular normalization." (PMID 32133779, 2020). "This is similar to the uncontrolled release of renin by some renal renin-secreting tumours; in one case it was shown that the fall in blood pressure correlated with the post-operative decline in plasma renin after the tumour was removed." (PMID 31551925, 2019). "As antihypertensive medicines, angiotensin-converting-enzyme inhibitors (ACEIs) and antihypertensive angiotensin receptor blockers (ARBs) target the renin-angiotensin system that has also been found to be involved in carcinogenesis by regulating cell proliferation and tumor growth." (PMID 27965461, 2017). "Renin‐producing cells in the adrenal gland have been localized to the zona glomerulosa in rat models, but have yet to be localized to a specific zone in a human tumor." (PMID 26997629, 2016). "It was identified that the tumor size had increased and the renin level was re-elevated." (PMID 25289084, 2014). "The correct diagnosis is based on the combination of macroscopic appearance of the tumor, light microscopy of the tumor cells, immunohistochemical staining for various cell markers (including renin), and typical ultrastructural finding of intracellular renin deposits." (PMID 25177679, 2014). "Messenger RNA of renin is found in the cytoplasm of tumor cells of JGCT." (PMID 21871063, 2011). "Immunohistochemically, tumor cells exhibit a positive reactivity for renin, vimentin and CD34." (PMID 21871063, 2011).
tumor (continued). "ACE2, part of the renin-angiotensin system (RAS), paradoxically plays both protective and tumor-promoting roles: while it mitigates angiotensin II-mediated damage in cardiovascular systems, its elevated expression in CRC is associated with increased tumor aggressiveness and poor prognosis." (PMID 41048966, 2025). "Our hypotesis that, by inhibiting angiogenesis, renin-angiotensin system inhibitors may reduce tumor growth and improve the effectiveness of cyclin-dependent kinase 4/6 inhibitors by cutting off the supply of nutrients and oxygen to the tumor." (PMID 41417371, 2025). "Furthermore, pathways related to the renin-angiotensin system may influence the tumor microenvironment, affecting cell signaling and tumor behavior." (PMID 39669201, 2024). "The tumor showed no or mild blood flow might be related to the vasoconstriction caused by renin and the decreased blood flow caused by the proliferation of intima and middle layer of tumor arterioles." (PMID 38365645, 2024). "Prior to this trial, preclinical data had demonstrated that angiotensin I receptor inhibitors, which block the renin-angiotensin system, could potentially impede tumor growth and metastasis and ameliorate the effectiveness of systemic therapy by increasing drug delivery to the tumor tissue." (PMID 37366887, 2023). "One of the hypothesised neoplastic mechanisms is related to the renin–angiotensin system, whereby angiotensin converting enzyme inhibitors might enhance angiogenesis via vascular endothelial growth factor and thus promote tumour progression." (PMID 35618844, 2022). "Anatomically distinct regions of the TME, known as tumor niches, are thought to contain CSCs and play a fundamental role in the regulation of metabolism, immune surveillance, survival, invasion, and self-maintenance with the renin–angiotensin system (RAS) playing a critical role." (PMID 34439159, 2021). "These analyses showed that our patient had a hyperreninemia with a secondary hyperaldosteronism (renin 266.4 microUI/mL, aldosterone 38.1 ng/dL), which could be due to the presence of a renovascular disease, a renin-secreting tumor, or a scleroderma renal crisis." (PMID 27389397, 2016). "Local renin-angiotensin systems exist in various malignant tumor tissues; this suggests that the main effector peptide, angiotensin II, could act as a key factor in tumor growth." (PMID 24465768, 2014). "Local renin-angiotensin systems exist in various malignant tumor tissues, which suggests that the main effector peptide, angiotensin II, could act as a key factor in tumor growth and angiogenesis via the angiotensin II type 1 receptor." (PMID 24465768, 2014). "The potential role of the renin-angiotensin system (RAS) in the promotion of tumour growth has been investigated, and the administration of RAS inhibitors, such as angiotensin-converting enzyme inhibitors (ACEIs) or angiotensin II receptor blockers (ARBs), may improve disease control in malignancy." (PMID 22187036, 2012). "Renin–angiotensin system (RAS) inhibitors, such as ACE inhibitors and ARBs, have been suggested to improve prognosis by modulating tumor microcirculation and suppressing proliferative signaling." (PMID 41303903, 2025). "Renin-angiotensin system inhibitors, including ACE inhibitors and angiotensin receptor blockers (ARBs), have demonstrated anti-tumor effects in preclinical models." (PMID 40940839, 2025). "REN maps on chromosome 17p, a region frequently deleted in SHH-MB subgroup, and acts as tumor suppressor which, by promoting degradation of HDAC1, inhibits GLI1 activity and represses SHH-MB growth." (PMID 38062245, 2024). "The results showed that ANXA5, MMP1, MTR, REN, SCN4A, and SMAD3 were upregulated in HC samples, while HP and ACOX1 were downregulated in tumor tissues." (PMID 38599581, 2024).
tumor (continued). "Proteomic analysis revealed that SALL4 interacts with REN/KCTD11 (here REN), a substrate receptor subunit of the Cullin3-RING ubiquitin ligase complex (CRL3REN) and a tumor suppressor lost in ~30% of human SHH-MBs." (PMID 38062245, 2024). "Immunostaining revealed strong anti-renin antibody staining, an unusual finding in AML that suggests renin production by the tumor." (PMID 39650950, 2024). "Secondary hyperaldosteronism is usually due to hyperactivity of the renin-angiotensin-aldosterone system (RAAS), usually due to a renin-producing tumor." (PMID 39759753, 2024). "The gene ANPEP/LOC112653425, involved in glutathione metabolism, the renin–angiotensin system, and hematopoietic cell lineage, was found to be one of the most prevalent DEGs in IBD enteroids and tumor enteroids." (PMID 35884586, 2022). "The renin-angiotensin system (RAS), besides being a major regulator of blood pressure, is also involved in tumor angiogenesis." (PMID 34898568, 2021). "Our demonstration that the renin-expressing myofibroblast can be propagated in culture provides a novel and unique tool to investigate specific roles of the ccRCC CAF in tumor biology." (PMID 34884982, 2021). "The systemic renin–angiotensin system (RAS) controls the cardiovascular system, and the local RAS is a key factor to tumor proliferation and metastasis in tumor microenvironment." (PMID 34221978, 2021). "The renin–angiotensin system (RAS) affects tumor growth and migration by remodeling the tumor microenvironment." (PMID 32969473, 2020). "The components of the renin-angiotensin system (RAS) including both, conventional and alternative axis, appear to have contradictory effects on tumor biology." (PMID 30464806, 2018). "In this setting of a suppressed plasma aldosterone concentration (PAC) and a suppressed plasma renin activity (PRA), a differential diagnosis of a deoxycorticosterone (DOC) producing tumor was entertained." (PMID 20671982, 2010). "Immunohistochemical staining of the tumour was positive for Renin, CD34, Vimentin, and synaptophysin (Syn) and negative for somatostatin receptor 2 (SSTR2) and chromogranin A (CgA)." (PMID 35303838, 2022). "In this context, the renin–angiotensin system (RAAS), which plays an important role in the relationships between the tumor microenvironment, the vasculature, and the immune system, has also been reported to participate in the process of tumor angiogenesis." (PMID 35804826, 2022). "Some studies also indicated that ACEIs/ARBs may have a benefit on cancer prognosis through blocking renin–angiotensin system (RAS) signal pathway and inhibiting tumor angiogenesis and tumor cell proliferation." (PMID 35443635, 2022). "Mutations within the components of the HH pathway, for example, membrane receptor proteins PTCH1 and SMO, non-membrane receptor proteins, such as SUFU and REN (KCTD11), disrupt the feedback loop causing activation of HH pathway and tumor progression." (PMID 33637972, 2021). "Intriguingly, inhibition of renin-angiotensin signaling in combination with the anti-VEGF drug Bevacizumab, inactivated tumor endothelial YAP and reduced the fibroblast-induced metastatic TME stiffness and tumor vasculature." (PMID 33614496, 2020). "Immunohistochemical staining showed no expression of renin in 19 samples, with one sample showing weak diffuse staining throughout the tumor (data not shown)." (PMID 33147716, 2020). "This ESC-like population expresses components of the renin-angiotensin system (RAS): pro(renin) receptor (PRR), angiotensin converting enzyme (ACE), angiotensin II receptor 1 (ATIIR1), and angiotensin II receptor 2 (ATIIR2) in the microvessels in this tumor." (PMID 30949483, 2019). "On pathological examination, the tumor tissue stained negative for chromogranin and positive for renin." (PMID 26997629, 2016). "Because epithelial markers, but not renin, were positive in the space-lining cells, the tubular architectures seemed to be derived from dilated tubules involved by the tumor." (PMID 23607027, 2013).